CCL2 (C-C motif chemokine ligand 2)
Diseases named in the same sentence as CCL2 in open-access papers (continued):
Sharing a sentence is not in itself a finding about the gene and the disease.
Obesity (continued). "Also, the high number of chemokines induced (most of which have redundant properties) supports the fact that leukocyte adipose tissue infiltration observed during obesity is not related to one or two proteins such as CCL2 or CCL5." (PMID 23824685, 2013). "Taken together, these results suggest that hyperlipidemia, which is common in obesity and metabolic syndrome, may be a confounding factor, and that the absence of CCL2 may be as metabolically deleterious as overexpression of CCL2 in certain conditions." (PMID 20936118, 2010). "Therefore, the higher levels of CCL2 in the ascites of obese WT mice may be derived not from tumoral tissues but from obesity-related, extra-tumoral tissues including adipocytes, as observed in adipose tissues." (PMID 34638514, 2021). "Therefore, our results highlight that PhyS-milk consumption may induce a shift towards a decreased inflammatory state through its effect on two key cytokines, CCL2/MCP-1 and IL-10, having thus a potential effect in the context of obesity where inflammatory pathways are exacerbated." (PMID 28608804, 2017). "In contrast, CCL2 was not different between VAT and SAT, but displayed an overall elevation in samples from subjects living with obesity." (PMID 36340033, 2022). "We found that, although there is no significant change in the level of chemokine (C-C motif) ligand 2 (CCL2) either in adipose tissue or in circulation, the cellularity of ATMs is dramatically elevated at the early stage of obesity." (PMID 27031964, 2016). "Instead, CCL2 (MCP-1), CCL11 (eotaxin), G-CSF, and CCL4 (MIP-1β) were decreased by exercise regardless of obesity status." (PMID 26110868, 2015). "As expected, patients with obesity (Groups II and III) showed significant elevations in plasma levels of triglycerides, nonesterified fatty acids, and inflammatory markers such as CCL2/MCP‐1, TNF‐α, plasma endotoxin (LPS), and LEP, along with a very significant increase in adipocyte size." (PMID 40518865, 2025). "More importantly, we also observed that freshly isolated fat cells from people living with obesity recapitulate our in vitro observations as they display ER stress, lower CKB expression, increased methylation of the CKB promoter and higher levels of CCL2 compared to non-obese individuals." (PMID 39675471, 2024). "Interestingly, our data suggest that inflammation modulated by IL-1β, IL-6, PLAUR, and CCL2 in the VAT could be related to anxiety and mood disorders as long as patients are not in an obesity state." (PMID 30504920, 2018).
COVID-19 (898 papers, 2020 to 2026). A disease caused by infection with severe acute respiratory syndrome coronavirus 2. "In this sense, other cytokines and chemokines such as MCP-1, IL-10, IL-15, CXCL10, and CCL2 have been associated with SARS-CoV-2 viremia." (PMID 35783606, 2022). "Mediated MR results revealed that CCL2 was a possible mediator of causality of family Bifidobacteriaceae and order Bifidobacteriales with COVID-19, mediating at a ratio of 12.73%." (PMID 38803488, 2024). "The detection of specific chemokines in the plasma at the mRNA and protein levels suggests that higher concentrations of CCL2 are associated with the severity of COVID-19, which has potential as a prognostic factor." (PMID 38455049, 2024). "Beyond cytokines, some chemokines are also implicated in the severity of COVID-19, acting as chemoattractants for immune cells, such as CCL2 or CXCL10, which contribute to the amplification of the inflammatory response." (PMID 39916956, 2024). "CXCL10, GM-CSF, VEGF, IL-1β and CCL2 were clearly positively associated with a higher COVID-19 severity in elderly patients even after adjustment for age and correction for multiple testing." (PMID 38715114, 2024). "Our results showed that the severe COVID-19 phenotype was associated with the co-occurrence of the CCL2 rs1024611-G, OAS1 rs1024611-A, and DPP9 rs10406145-G alleles." (PMID 38694517, 2024). "Both chemokines CCL2 and IP-10 have also been implicated in lymphopenia characteristically observed among patients with COVID-19." (PMID 37376437, 2023). "Like SPP1, CXCL10, and CCL2, whose plasma levels associate with COVID-19 severity, the plasma level of CCL18 was also found to be significantly different between patients with mild and critical COVID-19." (PMID 37917179, 2023). "CXCL10 and CCL2 are biomarkers that have been associated with disease severity and the risk of death in COVID-19 patients." (PMID 35958594, 2022). "Meanwhile, hyperinflammation associated with severe COVID-19 also encompasses the release of inflammatory chemokines such as CCL2, CCL3, and IP-10." (PMID 35647937, 2022). "With COVID-19, the increased CCL2 is not only associated with respiratory failure but also with extrapulmonary manifestations." (PMID 35464491, 2022). "Upon discharge, serum levels of CCL2, a biomarker known to correlate positively with mortality risk in COVID-19 patients, trended slightly lower in mild and moderate I patients than in moderate II patients." (PMID 36366324, 2022). "The bronchoalveolar fluid from severe/mild COVID-19 patients showed increased chemokine (C-C motif ligand-2: CCL-2) and CCL-7, attracting the CCL2-associated monocytes." (PMID 35784278, 2022). "Many of the upregulated genes annotated in the Coronavirus pathogenesis pathway, such as IL6 and CCL2, are associated with hypercytokinemia or cytokine storm, a systemic hyper-inflammatory state that has been shown to influence COVID-19 disease severity." (PMID 35945487, 2022). "A signature marker of COVID-19–associated coagulopathy is the presence of neutrophil extracellular traps, which recruit myeloid cells to the culprit site via CCL2." (PMID 35749425, 2022). "Their results revealed host inflammatory cytokine profiles to SARS-CoV-2 infection in patients and highlighted the association between COVID-19 pathogenesis and excessive cytokine releases such as CCL2/MCP-1, CXCL10/IP-10, CCL3/MIP-1A, and CCL4/MIP1B." (PMID 34441862, 2021). "Our results reveal distinct host inflammatory cytokine profiles to SARS-CoV-2 infection in patients, and highlight the association between COVID-19 pathogenesis and excessive cytokine release such as CCL2/MCP-1, CXCL10/IP-10, CCL3/MIP-1A, and CCL4/MIP1B." (PMID 32228226, 2020).
COVID-19 (continued). "This study highlights the associations of the IL-6 rs1800796 (-572 G/C), IL-10 rs1800871 (-819 C/T), rs1800872 (-592 C/A) and CCL5 rs2107538 polymorphisms with fatal COVID-19 outcomes and elevation of cytokines (CCL-2, IL-6, IL-10 and CXC-L10) plays a crucial role in the pathogenesis of COVID-19." (PMID 40881695, 2025). "Among them, serum levels of IL-10RB, FGF-19, and CCL-2 positively contributed to both hospitalized and critical COVID-19 conditions (OR: 1.10~1.16), while the other 4 proteins conferred risk on critical COVID-19 only (OR: 1.07~1.16), including EIF4EBP1, IL-7, NTF3, and LIF." (PMID 38455043, 2024). "When the GG genotype of the CCL2 rs1024611 gene variant was examined among individuals with different clinical manifestations of COVID-19, its distribution was associated with an increased association with the severe COVID-19 phenotype in a recessive model (P = 0.0003, OR = 6.43, 95% CI 2.19-18.89)." (PMID 38694517, 2024). "Mediated MR results indicated that CCL2 may be a mediator of the causal relationship between family Bifidobacteriaceae and order Bifidobacteriales to COVID-19, with a mediation ratio of 12.73%." (PMID 38803488, 2024). "According to multivariate logistic regression analysis, the CCL2 rs1024611-GG genotype may be independently associated with severe COVID-19." (PMID 38694517, 2024). "The Two-step MR results indicated that CCL2 may act as a mediator in the causal relationship between family Bifidobacteriaceae and order Bifidobacteriales and COVID-19, with a mediation ratio of 12.73%." (PMID 38803488, 2024). "Suggesting a genetic causation between specific gut microbiota and COVID-19, our present research emphasizes the underlying mediating role of CCL2, an inflammatory factor, and contributes to a deeper understanding of the mechanism of action underlying COVID-19." (PMID 38803488, 2024). "Moreover, the literature-based pathway analysis uncovered a set of specific genes, such as CALCA, ACE, SIRT1, TNF, IL6, CCL2, and others, that were found to mediate the association between OA and COVID-19." (PMID 38020136, 2023). "In addition to a suggestive association between CCL2-A2518G gene variants and the severity of COVID-19, a genome-wide study showed associations between the risk of severe COVID-19 and a multigene locus at 3p21.31 and the ABO blood group locus at 9q34.2." (PMID 37198402, 2023). "CCL2 is an important chemokine associated with the severity of COVID-19." (PMID 35327350, 2022). "In COVID-19, a significant reduction of the inflammatory process related to CCL-2/MCP-1 and CXCL8/IL-8 activity might be associated with the exercise protocol with controlled intensity and duration." (PMID 36685603, 2022). "CCL2 has been linked to influenza induced disease severity in an animal model and documented as one of the significantly increased chemokines in severe COVID-19 hyperinflammation syndrome." (PMID 35784346, 2022). "We therefore predict that each of the CCR2 and CCR5 receptors has a complementary role in infection-associated inflammation and tissue sequelae in COVID-19 with CCR2/CCL2 seen in both early and late stages of infection and CCR5/CCL5 seen later in the infectious process." (PMID 35749425, 2022). "Furthermore, in the peripheral blood mononuclear cells (PBMCs) isolated from the BALF of patients with COVID-19, overexpression of a set of genes encoding for several chemokines, including CCL2, CXCL10, CCL3, and CCL4, was recorded." (PMID 33946736, 2021). "Strikingly, our study, and two recent investigations carrying out single cell RNA sequencing of immune cells and cytokine determinations in BAL, converge in a major pathogenic role of IL-1 β, IL-6, and CCL2 in patients who develop severe COVID-19 compared to people with less severe disease." (PMID 33995342, 2021).
COVID-19 (continued). "However, Patients infected with SARS-CoV-2 who have the TNF-α gene variant (rs1800629) are protected from developing COVID-19 moderate and severe outcomes, as well as from presenting low concentrations of some pro-inflammatory cytokines and chemokines (IL-6, CCL2, and CXCL-10)." (PMID 40881695, 2025). "Thus, individuals with the GG genotype may have a higher expression of CCL2 and, consequently, a higher attraction of monocytes and macrophages, which is associated with the severe COVID-19 phenotype." (PMID 38694517, 2024). "Notably, the relative abundance of Prevotella in the nasopharyngeal microbiota was found to be positively associated with COVID-19 severity, which may be due to its association with the nasopharyngeal cytokines CCL2 and VEGF." (PMID 36350127, 2022). "Similarly, we also observed that GABA treatment slightly reduced the levels of serum CCL2 which may have contributed to protecting mice from death since high levels of CCL2 are associated with high mortality in COVID-19 patients." (PMID 36389819, 2022). "The serum SP-D, CCL2/MCP-1, and IL-18 concentrations were significantly higher in the COVID-19 patients before admission to the hospital than those in the controls (p < 0.001 for all comparisons)." (PMID 42196173, 2026). "CCL2 is secreted during the early phase of infection and is significantly increased further during late stages of fatal cases than severe and/or mild COVID-19 patients." (PMID 40552037, 2025). "These higher levels of CCL2 correlate with increased severity and higher mortality in COVID-19 patients." (PMID 40584180, 2025). "We observed a trend toward increased CCL2 levels with the outcomes of the COVID-19 patients, as well as, of IL-1Ra and CCL3 levels being elevated in patients with severe disease." (PMID 40881695, 2025). "The CCL2–CCR2 pathway is a recognized amplifier of COVID-19 lung inflammation during acute disease, and elevated CCL2 has been documented in respiratory specimens and blood of severe cases." (PMID 41440526, 2025). "The chemokine (C-C motif) ligand 2 (CCL2/ also known as monocyte chemoattractant protein 1 (MCP1) and its cognate receptor (CCR2) are unregulated in COVID-19 patients and is linked to predict the severity of disease." (PMID 40552037, 2025). "We detected significant upregulation of the neuropilin ligand TGFB1 and chemokine CCL2 in monocytes from fatal COVID-19 cases." (PMID 41159753, 2025). "Recent evidence indicates that bronchoalveolar lavage CCL2 concentrations correlate with radiographic fibrosis severity in post-COVID-19 pulmonary fibrosis, suggesting a conserved mechanism across different fibrotic lung pathologies." (PMID 40650314, 2025). "Our data reveal a shift towards a pro-inflammatory M1 phenotype in severe COVID-19 cases, with elevated expression of TNFα, IL1β, CCL2, and CCL3, which are markers of classical activation and inflammation." (PMID 39928675, 2025). "The C-C motif ligand 2 (CCL2) is significantly involved in the pathogenesis of the breathing complexities that define the most severe form of COVID-19." (PMID 39024368, 2024). "The levels of CCL-2 were reported to be elevated in COVID-19 patients compared to healthy individuals, especially those infected with ancestral, alpha, and omicron SARS-CoV-2 variants." (PMID 38646483, 2024). "This analysis highlighted the link from the gut microbiota to COVID-19, highlighting the mediating role of the inflammatory protein CCL2." (PMID 38803488, 2024). "We note the differential expression of many inflammatory CC chemokines (CCLs) in severe COVID-19, including CCL2, CCL3, CCL8, CCL3L1 and CCL7, and CXC chemokines such as CXCL2 and CXCL8." (PMID 39187683, 2024). "Two-step MR and bidirectional MR analyses were performed to examine the mediating pathways from order Bifidobacteriales through CCL2 to COVID-19, and family Bifidobacteriaceae through CCL2 to COVID-19." (PMID 38803488, 2024).
COVID-19 (continued). "During severe COVID-19, CCL2 secretion in the lung likely participates to unconventional monocyte lung infiltration linked with pathogenesis." (PMID 38715114, 2024). "We found that a high level of the senescence-associated cytokines GM-CSF, CXCL10, VEGF and CCL2, NLR, and a high CD27−CD28− percentage among CD8+ T cells, were positively associated with increased COVID-19 severity." (PMID 38715114, 2024). "In association with other inflammatory cytokines, the increase in CCL2/MCP-1 in COVID-19 leads to harmful disease progression and induces acute kidney injury in critically ill patients." (PMID 39281667, 2024). "Analysis of haplotype frequencies revealed that the coexistence of GAG at CCL2, OAS1, and DPP9 variants, respectively, in the same individual increased the presence of the severe COVID-19 phenotype (OR=2.273, 95% CI: 1.271-4.068, P=0.005305)." (PMID 38694517, 2024). "The correlation with plasma MCP-1 (CCL2) and IP-10 is intriguing since these two markers are associated with COVID-19 disease severity." (PMID 38238298, 2024). "The present study focused on the association between the SNVs CCL2 rs1024611, OAS1 rs10774671, and DPP9 rs10406145 and severe COVID-19 in a population from Quito, Ecuador." (PMID 38694517, 2024). "Haplotype frequency analysis revealed that the coexistence of CCL2 rs1024611-G, OAS1 rs10774671-A, and DPP9 rs10406145-G alleles in the same individual increased the presence of the severe COVID-19 phenotype (OR=2.273, 95% CI: 1.271-4.068, P=0.005305)." (PMID 38694517, 2024). "Similar to CCL-2, CCL-4 was also reported to be elevated in COVID-19 patients and correlated to several variants." (PMID 38646483, 2024). "Surprisingly, HUVECs incubated with severe COVID-19 serum also showed a decrease in the expression of CCL2, IL6, TNFa, PTGS2, and ITGAM compared with the control that received or did not receive pretreatment with PC." (PMID 39066212, 2024). "Analysis of cytokine profiles showed increased plasma levels of IP-10, HGF, VEGF-A, IL-7, IL-18, and MCP-1/CCL2 in COVID-19 patients." (PMID 38486975, 2024). "The secretion of cytokines and chemokines, including IL6, CXCL8, IL1B, IL10 and CCL2, is significantly increased in COVID-19 AKI." (PMID 37274117, 2023). "Monocytes from HD + COVID-19 patients showed an enhanced capacity for pro-inflammatory cytokine production, with GM-CSF, IL-1β, IL-8, IL-10, CCL2 and CCL3 as the most increased cytokines compared with uninfected HD patients." (PMID 36675231, 2023). "Evidence from clinical studies indicates that the severity of COVID-19 is positively associated with chemokine and inflammatory cytokine levels in the plasma of patients, such as TNF-α, IL-1β, IL-6, CCL2, CCL8, and CXCL9." (PMID 38104081, 2023). "Strikingly, the four chemokines: Ccl2, Cxcl9, Cxcl10, and Cxl11, involved in the COVID-19 cytokine storm and found upregulated in both species in the present work, were also found to be overexpressed upon type I interferon application in vitro." (PMID 37350967, 2023). "Post–COVID-19 MDMs showed higher expression of proinflammatory chemokines (CCL2, CCL8, and CCL7), driving neutrophil recruitment, including in COVID-19." (PMID 36668902, 2023). "In severe cases, through inflammatory mediators like IFN-α, IL-1β, IL-6, CCL2, CCL5 and others, COVID-19 causes an inflammatory process that if uncontrolled evolves into lung tissue injuries, systemic inflammations and pathogenesis, and organ failure." (PMID 37662953, 2023). "Specifically, CCL2 and CXCL10 have been associated with an increased risk of death and poor prognosis in COVID-19 patients." (PMID 37497545, 2023). "It was evident that the distribution of the ΔCt-values of the CCL2 genewas broader in COVID-19 patients compared to healthy controls." (PMID 37832397, 2023).